HNF1A (HNF1 homeobox A)
Diseases named in the same sentence as HNF1A in open-access papers (continued):
Sharing a sentence is not in itself a finding about the gene and the disease.
MODY (continued). "Secondly, since MODY is known to be a disorder of haploinsufficiency, we cannot rule out the possibility that there may also be species-specific differences in the dosage of the HNF1A, HNF1B and HNF4A gene products that are required for full function." (PMID 19924231, 2009). "No HNF1A mutations causative of MODY have been found, as well." (PMID 19490620, 2009). "Besides, classical MODY has been excluded by complete sequencing of HNF1A and GCK genes." (PMID 19490620, 2009). "Strong genetic evidence confirms the etiological role of HNF1A, HNF4A, and GCK genes in the development of MODY." (PMID 39859454, 2025). "GCK-MODY leads to stable and mild fasting hyperglycemia due to reduced glucokinase enzyme activity and typically does not require pharmacologic treatment, whereas HNF1A-MODY and HNF4A-MODY are associated with progressive β-cell dysfunction and are often highly responsive to sulfonylurea therapy." (PMID 41367630, 2025). "Typically, low-dose sulfonylurea medications are effective in treating both HNF1A- and HNF4A-MODY patients, although other oral hypoglycemic agents have also been shown to improve blood glucose control." (PMID 40149950, 2025). "Although DKA is relatively rare, there are relevant reports, observed in some types of MODY, such as INS-, PDX1-, NEUROD1-, HNF1A- and HNF1B-MODY." (PMID 40303944, 2025). "In this study we focused on the HNF1A, HNF4A and HNF1B genes (collectively referred to as HNF-MODY)." (PMID 40925988, 2025). "In both HNF1A- and HNF4A-MODY, tirzepatide has since been used in routine practice to achieve better glucose and weight outcomes, while allowing patients to reduce or discontinue other agents." (PMID 41262822, 2025). "The most common MODY subtypes include GCK-(MODY2), HNF1A-(MODY3), HNF4A-(MODY3) and HNF1B-(MODY5), accounting for over 80% of all MODY cases." (PMID 40303944, 2025). "In Korean patients, the most common form of MODY was GCK gene lesions (50%), followed by HNF1A (21.4%) and HNF4A (21.4%) genes." (PMID 39902162, 2024). "We identified 1640 individuals with MODY in the DPV registry, with GCK (n = 941) and HNF1A (n = 417) as the most common MODY types." (PMID 39511990, 2024). "GCK-MODY(MODY2) and HNF1A-MODY(MODY3) are the two most common forms of the disease, accounting for more than 80% of patients with MODY from European populations, whereas 80% of Japanese and Chinese patients with MODY do not have lesions in known MODY genes." (PMID 39902162, 2024). "All 14 known MODY types are represented in the registry, with GCK‐MODY (n = 941) and HNF1A‐MODY (n = 417) as the most frequent types." (PMID 39511990, 2024). "The most common forms of MODY in adults include GCK-MODY (30%–50%) and HNF1A-MODY (30%–50%) while HNF4A-MODY is much rarer (2%–5%)." (PMID 38933924, 2024). "It has been suggested that HNF1A/HNF4A-MODY can present at up to 45 years of age and should be included as an age cut-off to consider all possible cases of this MODY subtype." (PMID 37234800, 2023). "Chinese research also identified the prevalence of HNF1A-MODY and GCK-MODY was only 9% and 1% in patients with suspected MODY." (PMID 35921062, 2022). "A retrospective database study of MODY cases reported in Brazil described GCK-MODY as the most common form, followed by HNF1A-MODY." (PMID 35592779, 2022). "We excluded the possibility that these patients present the most common forms of MODY by sequencing GCK, HNF1A and HNF4A." (PMID 35625914, 2022). "The most common forms of MODY are caused by mutations in the glucokinase gene (GCK-MODY) and hepatocyte nuclear factor genes (HNF1A-, HNF1B- and HNF4A-MODY) which together are responsible for around 99% of all MODY cases." (PMID 34299172, 2021). "In another MODY genetic screening study of 76 unrelated families, GCK, HNF1A and HNF4A accounted for 18.42%, 15.79% and 2.63% of all MODY cases, respectively." (PMID 34421822, 2021).
MODY (continued). "In this study, we focused on the four most common MODY genes (HNF4α, GCK, HNF1α, and HNF1β) and performed screening analysis of 45 Japanese pediatric patients who were between 2.8 and 17 years of age at diagnosis." (PMID 34746319, 2021). "Some MODY subtypes (e.g., ABCC8, KCNJ11, HNF1α, and HNF4α MODY) are manageable through KATP inhibition — i.e., sulfonylurea use." (PMID 34032641, 2021). "However, heterozygous mutations in the GCK (glucokinase) (MODY 2), HNF1A (hepatocyte nuclear factor 1 alpha) (MODY 3), and HNF4A (hepatocyte nuclear factor 4 alpha) (MODY 1) genes are the most frequent, and together they explain over 95% of the known genetic causes of MODY." (PMID 31968686, 2020). "The GCK, HNF1A, and HNF4A genes were sequenced in 46 unrelated patients that had at least two of the three classical clinical criteria for MODY (age at diagnosis, family history, and clinical presentation)." (PMID 31968686, 2020). "Enlightening the role of HNF1A in β-cells would be helpful in understanding the molecular mechanism of both T2DM and MODY and would guide new therapeutic approaches." (PMID 31109344, 2019). "To date, 14 disease genes for MODY are identified; most of them are transcription factors MODY1 (HNF4A), MODY3 (HNF1A), MODY4 (PDX1), MODY5 (HNF1B), MODY6 (NEUROD1/BETA2), MODY7 (KLF11), MODY8 (CEL), MODY9 (PAX4), MODY11 (BLK), and MODY14 (APPL1)." (PMID 31145732, 2019). "To summarize, we have shown that a single dose of dapagliflozin, an SGLT-2 inhibitor, induces higher glycosuria in HNF1A- and GCK-MODY than in T2DM." (PMID 28593615, 2017). "Here, in this short, 24 h clinical experiment, we show for the first time that dapagliflozin induces glycosuria in both HNF1A-MODY and GCK-MODY patients and reduces FPG in GCK-MODY." (PMID 28593615, 2017). "Mutations in hepatocyte nuclear factor 4 alpha, (HNF4A, MODY1), glucokinase (GCK, MODY2), hepatocyte nuclear factor 1 alpha (HNF1A, MODY3) result in most common forms of MODY." (PMID 26300908, 2015). "For example, most laboratories will first screen HNF1A, followed by HNF4A and GCK in subjects exhibiting the classical features of MODY; and first GCK, then HNF1A and HNF4A, if the diabetic phenotype is mild and fasting glucose 5.5–8.5 mmol/l." (PMID 22662265, 2012). "MODY and RCAD are autosomal dominant disorders, thought to be mediated by a haploinsufficiency-based mechanism due to a reduced amount of HNF-1α, HNF-1β or HNF-4α proteins." (PMID 19924231, 2009). "Both HNF1A(B) and HNF1A(C) contain novel amino acids derived from intronic sequences and it seems plausible that mutations in these regions, not currently screened by sequencing, could cause MODY." (PMID 19787084, 2008). "Studies have shown that de novo mutations in common MODY genes such as HNF1A, HNF4A, and GCK occur in approximately 7% of MODY cases without a family history, underscoring the importance of considering MODY even in the absence of familial diabetes." (PMID 41020216, 2025). "One disease that is particularly troublesome to identify is maturity‐onset diabetes of the young (MODY), which is a monogenic diabetic disease whose most prevalent types are glucokinase (GCK)‐MODY, hepatocyte nuclear factor 1‐α (HNF1A)‐MODY, and hepatocyte nuclear factor 4‐α MODY." (PMID 37226652, 2023). "In the Gulf Cooperation Council (GCC) region, a study from Oman examined 20 patients with suspected MODY but found no variants in three MODY genes (HNF4A, GCK, and HNF1A) sequenced at Exeter20." (PMID 34373539, 2021). "In 46 families with clinically suspected MODY, mutations were found in 23 (50%) families, including seven GCK, HNF1A, and HNF4A mutations that have not previously been reported." (PMID 31968686, 2020). "In the other two studies with Brazilian cohorts, approximately 60% of patients with clinical suspicion of MDM did not have mutations in HNF1A, GCK or HNF4A genes, but we did not test other MODY genes." (PMID 31576961, 2020).
MODY (continued). "Individuals from the UK with GCK- or HNF1A/HNF4A-MODY who were not on recommended treatment at the time of genetic diagnosis, and who were diagnosed below the age of 30 years and were currently aged less than 50 years, were eligible to participate." (PMID 30229274, 2018). "In contrast, HNF1A- and HNF4A-MODY patients can be treated with low-dose sulfonylureas." (PMID 28314945, 2017). "To identify patients with novel heterozygous PTVs, we first assessed 38 European (non-Finnish) probands with a strong MODY-like phenotype who did not have mutations in the common MODY genes (GCK, HNF1A, HNF4A) by Sanger sequencing." (PMID 29026101, 2017). "Of the five 10−5 cutoff genes in MODY, HNF1A and HNF1B were absent in 10−8 set while the latter alone was missing from 10−7 and 10−6 gene lists." (PMID 23308243, 2013). "There has been no prospective study performed to date on subjects with HNF1A-MODY with regards to macrovascular complications." (PMID 24069322, 2013). "Coding sequences of the genes causing MODY1-4 and MODY6 (GCK, HNF1A, IPF1, NEUROD1, and HNF4A) were sequenced in the proband to rule out known causes of MODY with compatible clinical presentations." (PMID 19216786, 2009). "It is well established that patients affected by GCK-MODY do not require any pharmacological treatment, while patients with HNF1A or HNF4A-MODY have a good response to sulfonylureas in term of glycaemic control and prevention of micro- and macrovascular complications." (PMID 34496959, 2021). "Sanger sequencing for mutations in GCK, HNF1A, and HNF4A (the most common MODY genes) was negative." (PMID 34032641, 2021). "Hyperglycaemia has a negative impact on the cardiovascular system, although the glycaemic index of HNF1A-MODY patients may not be the main reason for this high mortality." (PMID 34299172, 2021). "Seven variants (GCK c.494T>C, GCK c.563C>G, HNF1A c.1623G>A, HNF1A c.1729C>G, HNF4A c.68delG, HNF4A c.422G>C, HNF4A c.602A>C) have not previously been reported in patients with MODY and were found to be absent or very rare (≤0.0001) in the gnomAD population database." (PMID 31968686, 2020). "Since the disease gene, HNF1A, of our MODY3-iPSCs is categorized as a transcription factor, while glucokinase in MODY2-iPSCs is categorized as an enzyme, it is suggested that different mechanisms may contribute to the pathophysiology of MODY." (PMID 31145732, 2019). "To elucidate the pathology of MODY, we established MODY3 patient-derived iPS (MODY3-iPS) cells using non-integrating Sendai virus (SeV) vector and examined the mutant mRNA and protein of HNF1A (Hepatocyte Nuclear factor 1A) after pancreatic lineage differentiation." (PMID 31145732, 2019). "The additional expense and inconvenience of injection therapy does not appear to justify routine GLP1 therapy in HNF1A-MODY, and it is unknown how effective these agents would be in the context of long duration MODY with secondary SU failure." (PMID 30377832, 2018). "This may be more pronounced in islet-cells, where Hnf1α and Hnf4α concentrations are much lower than in liver and other tissues that are not clinically afflicted in MODY." (PMID 20523905, 2010). "A correct genetic diagnosis of MODY may alter the therapeutic approach: patients with glucokinase (GCK) MODY usually do not require pharmacological treatment, and those with either hepatocyte nuclear factor 4-α (HNF4A) or hepatocyte nuclear factor 4-α (HNF1A) MODY are very sensitive to sulfonylurea." (PMID 32411229, 2020). "Furthermore, the elevated expression levels of miR-103 and miR-224 could be detected in the serum of HNF1α-MODY carriers compared with MODY-negative family controls." (PMID 29867778, 2018). "Recent study has revealed much higher frequency of spontaneous de-novo mutations in GCK, HNF1A and HNF4A genes than previously assumed; moreover in GCK-MODY, discrete fasting hyperglycaemia may not be yet recognized in a parent, thus, family history could be seemingly negative." (PMID 30013516, 2018).
MODY (continued). "Besides, HNF1a mutations have also been implicated in diabetic nephropathy related to type 1 diabetes and non-insulin-dependent, type 2 diabetes mellitus (T2DM), albeit not as pronounced as in MODY disorders." (PMID 25057215, 2014). "However, it is still possible that utilizing hsCRP as a biomarker alone for diagnosing HNF1A-MODY in a subject with an HbA1c >9% may yield a false negative result." (PMID 23803251, 2013). "GCK-MODY typically does not require drug therapy, whereas other forms of MODY, such as HNF1A, HNF4A, and KCNJ11, generally respond well to sulfonylurea therapy." (PMID 40149950, 2025). "In contrast, MODY generally does not require insulin treatment (especially GCK-MODY), although some subtypes (such as HNF1A-MODY) may necessitate insulin therapy as the condition progresses." (PMID 40520227, 2025).
type 2 diabetes (174 papers, 2004 to 2026). "The transcription factors HNF4A (MODY1) and HNF1A (MODY3) are best known as causes of maturity-onset diabetes of the young." (PMID 41614934, 2026). "Sulfonylureas constitute the standard therapy for patients with HNF1A-MODY (maturity-onset diabetes of the young) but are characterized by an increased risk of hypoglycemia." (PMID 39903441, 2025). "HNF1A is a well-known transcription factor, and its variants are strongly associated with the development of maturity-onset diabetes of the young (MMODY)." (PMID 40332430, 2025). "HNF1A variants have previously been associated with an elevated risk of gestational and type II diabetes mellitus, primarily through their role in promoting insulin resistance." (PMID 40573148, 2025). "On the other hand, the polygenic risk score for the common form of type 2 diabetes also jointly advanced the age of diagnosis of HNF1A-MODY." (PMID 39579208, 2025). "Heterozygous mutations in HNF1A are sufficient to cause the most frequent form of the maturity onset diabetes of the young (MODY)." (PMID 38731945, 2024). "These variants increase HNF1A transcriptional activity by up to 50% and provide a protective effect against type 2 diabetes." (PMID 39902162, 2024). "Large-scale genetic studies have clarified that the common variants of HNF1α and HNF4α genes are also associated with type 2 diabetes, suggesting that they are involved in the pathogenesis of both diseases." (PMID 39228912, 2024). "We also examine how an individual’s polygenic susceptibility, assessed using a PRS, affects the impact of rare HNF1A variants on type 2 diabetes." (PMID 36216889, 2023). "Few studies have examined the association between rare HNF1A variants and type 2 diabetes at a population level." (PMID 36216889, 2023). "MODY3, which is caused by mutations in HNF1A, is the most common form of maturity onset diabetes of the young." (PMID 37691384, 2023). "While only few individuals carry these rare variants in HNF1A, those who do have a substantially increased risk of type 2 diabetes." (PMID 36216889, 2023). "Here, we examine the association between rare functionally damaging HNF1A variants and type 2 diabetes in the ancestrally diverse Mount Sinai BioMe Biobank and the less diverse population-based UK Biobank, together comprising almost 180,000 individuals." (PMID 36216889, 2023). "We show that rare functional HNF1A variants, in particular those located in the functional domains, increase the risk of type 2 diabetes, at least among individuals of European ancestry." (PMID 36216889, 2023). "We examined the contribution of rare HNF1A variants to type 2 diabetes risk and age of diagnosis, and the extent to which their impact is affected by overall genetic susceptibility, across three ancestry groups." (PMID 36216889, 2023). "In an exome-wide analysis in 3756 Mexican and US Latino individuals, p.E508K in HNF1A was the only variant significantly associated with risk of type 2 diabetes (OR 5.48)." (PMID 36216889, 2023). "Using data from more than 180,000 individuals across three ancestry groups, from two biobanks, we observed that functional HNF1A variants are associated with an increased risk of type 2 diabetes, but only in individuals of European ancestry." (PMID 36216889, 2023). "Of further interest is that, in the European ancestry population, the association between functional domain HNF1A variants and type 2 diabetes is more pronounced in individuals with a high polygenic burden." (PMID 36216889, 2023). "The phenolic compounds in berry and citrus can be interacted directly with the dimerization domains of hepatocyte nuclear factor-1α (HNF-1α, a TF supporting the transcription of proteins linked with type II diabetes)." (PMID 36837850, 2023). "Heterozygous variants in the hepatocyte nuclear factor 1a (HNF1a) cause MODY3 (maturity-onset diabetes of the young, type 3)." (PMID 36361808, 2022).